COMT (catechol-O-methyltransferase)
Diseases named in the same sentence as COMT in open-access papers (continued):
Sharing a sentence is not in itself a finding about the gene and the disease.
infection (18 papers, 2014 to 2025). The state of being infected such as from the introduction of a foreign agent such as serum, vaccine, antigenic substance or organism. "As a subset of patients with CFS suffers from susceptibility to infections, we analyzed if COMT SNPs are associated with infections." (PMID 26272340, 2015). "For example, caffeic acid (5-hydroxyconiferaldehyde) O-methyltransferase (COMT) which is one of the enzymes involved in the lignin biosynthesis pathway did not change in Gladiator but was decreased in abundance in Iwa after infection." (PMID 35752627, 2022). "COMT, CCOMT and CSE are associated with lignin biosynthesis, which is beneficial for the lignification of the cell wall in response to pathogen infection." (PMID 29898655, 2018). "Expression of genes of the phenylpropanoid pathway (PAL, HCT, CCoAOMT, COMT and GT) was strongly induced during the later stages of seedling infection with F. oxysporum and increased during the time of infection." (PMID 27005923, 2016). "Our results indicate a relationship of COMT polymorphism rs4680 with immune dysregulation in CFS providing a potential link for the association between stress and infection susceptibility in CFS." (PMID 26272340, 2015). "This study found that the content of chlorogenic acid and neochlorogenic acid significantly increased during the mild infection stage, suggesting that COMT may drive the accumulation of these phenolic acid defense substances to combat rust disease infection." (PMID 40872211, 2025). "Lower abundance of COMT, which are involved in the synthesis of lignin in the oil palm roots, may possibly indicate severity of infection." (PMID 24663087, 2014). "COMT might augment inflammation and infection by influencing vascular function." (PMID 28825621, 2017). "On infection of honeyberry seedlings by F. foetens, the expression levels of genes 4CL1, 4CL2, POD1, HCT, COMT, and PAL from the phenylpropanoid biosynthesis pathway were significantly higher than those in CK." (PMID 41470700, 2025). "In the early stage of infection by Foc1, PAL, C4H, 4CL, CCR1, and COMT were up-regulated, and only one 4CL and one CCR1 were down-regulated, whereas CCoAOMT was up-regulated, and one F5H was down-regulated after Foc4 infection." (PMID 33176672, 2020). "In response to pathogen infection, there were 55 DEGs involved in this pathway, and found these DEGs were involved in the synthesis of various important proteins, such as PAL, CSE, CCoAOMT, COMT and POD, which were upregulated in LYBH2, LYBH3 and LYBH4." (PMID 39205945, 2024). "The interaction term (PC NCFxG) revealed to be the most strongly correlated with the neurobehavioral outcomes, indicating the interactions between genotypes (COMT, BDNF) and neonatal factors (infection, invasive procedures, surgery, GA), which were mainly loaded on CA4/DG and alveus." (PMID 30941021, 2019). "qRT‐PCR analysis indicated the absence of sugarcane yellow virus (SCYLV) infection in COMT mutant or WT plants." (PMID 28905511, 2018). "Higher mRNA levels of MAOA, MAOB and VMAT2 were observed upon infection in these cells also, while DBH and COMT expression was not significantly altered." (PMID 36611805, 2022).
cardiovascular disease (11 papers, 2009 to 2024). "Individuals with MTHFR, FUT2, and COMT variants can be categorized into high- or low-risk groups for conditions like cardiovascular disease, cognitive dysfunction, or nutrient deficiencies." (PMID 39642577, 2024). "The COMT Val158Met has also been reported to be associated with cardiovascular disease and metabolic disorder." (PMID 30045690, 2018). "A larger sample size can be the key to progress in establishing the genetic co-relationship of COMT polymorphism and cardiovascular disease." (PMID 30011860, 2018). "A larger sample size could be key to establishing the genetic co-relation of COMT polymorphism and cardiovascular disease." (PMID 30011860, 2018). "COMT polymorphisms have also been associated with the development of disorders such as cardiovascular disease and estrogen-induced hormonal cancers, which are characterized by increased levels of catecholamines and their reactive products in peripheral tissues." (PMID 19365560, 2009). "The genetic variation in catechol-O-methyltransferase (COMT), an enzyme that degrades catecholamines, is linked to cardiometabolic risk factors and incident cardiovascular disease (CVD)." (PMID 39085321, 2024).
neurodegenerative disease (8 papers, 2020 to 2024). A disorder of the central nervous system characterized by gradual and progressive loss of neural tissue and neurologic function. "Given that PD is one of the fastest-growing neurodegenerative diseases worldwide, there is a need to establish a clear framework for the systematic distribution of COMT-Is, considering inter-individual and intra-individual variations in patient response." (PMID 39338193, 2024). "Genetic factors such as SCN1B-SCN4B and COMT have been reported to contribute to chronic pain in neurodegenerative disease." (PMID 36291662, 2022). "However, compounds with a catechol group reserve outstanding properties by acting as potential therapeutic agents against oxidative stress, inflammatory processes, as neuroprotectors slowing the progression of neurodegenerative diseases and as catechol O-methyltransferase (COMT) inhibitors." (PMID 38672695, 2024). "Seven genes were observed to be involved in both infections of three coronaviruses and two neurodegenerative diseases, including the HSP90AA1, ALDH2, CAV1, COMT, MTOR, IGF2R and HSPA1A." (PMID 37015947, 2023).
neurological disorders (8 papers, 2007 to 2025). "Several common population SNPs of COMT were significant in genome-wide association studies of addictive behavior, cognition, and mood and neurological disorders." (PMID 38355921, 2024). "Similarly, COMT analysis showed an increase in the frequency of the intermediate metabolizer phenotype from 47% (Group A) to 68% in Group B. COMT enzyme activity is linked to various psychiatric and neurological disorders." (PMID 37759556, 2023). "Drugs targeting COMT are used in the treatment of neurological disorders such as Parkinson’s disease." (PMID 38355921, 2024). "The COMT and DBH genes are physically located at chromosomes 22q11 and 9q34, respectively, and both COMT and DBH are involved in catecholamine metabolism and are strong candidates for certain psychiatric and neurological disorders." (PMID 18466599, 2007).
neurodevelopmental disorder (5 papers, 2017 to 2022). A behavioral and cognitive disorder with onset during the developmental period that involves impaired or aberrant development of intellectual, motor, or social functions. "However, the exact mechanisms linking COMT, dopaminergic function and compulsive behaviour for individuals with neurodevelopmental disorders requires further investigation." (PMID 32862204, 2021).
metabolic disorders (4 papers, 2017 to 2024). "Therefore, the COMT enzyme has been implicated in multiple neuropsychiatric disorders and metabolic disorders." (PMID 37974041, 2023).
movement disorder (4 papers, 2012 to 2025). Neurological conditions resulting in abnormal voluntary or involuntary movement, which may impact the speed, fluency, quality and ease of movement. "Seventy patients from 18 Neurology and Movement Disorders Units across Spain were evaluable at data cut-off (July 2023), all of whom had started COMT inhibition with opicapone." (PMID 40426702, 2025). "In a population with chronic mental illness, various SNPs in 10 candidate genes (PPP1R1B, BDNF, DRD3, DRD2, HTR2A, HTR2C, COMT, MnSOD, CYP1A2, and RGS2) reached nominally significant (p≤0.05) associations with drug-induced movement disorder." (PMID 22615781, 2012).
Heart Disease (3 papers, 2005 to 2007). "The fact that we found that the COMT polymorphism modified the effect of ET on MPD in the EPAT study but not in the WELL-HART study suggests that the women with angiographically detected heart disease in the WELL-HART study might have been different." (PMID 15987428, 2005). "Few other studies have evaluated the influence of COMT genotypes on heart diseases." (PMID 17577421, 2007).
bacterial infection (1 paper, 2021). "In contrast, completely devoid of S-lignin fah1-2 and omt1-2 mutants deficient in F5H and COMT activity, respectively, albeit showed normal lignin levels, they did not become susceptible to bacterial infection." (PMID 34445148, 2021).
brain disorder (1 paper, 2023). A disease affecting the brain or part of the brain. "COMT regulates dopamine prefrontal levels and its altered activity has been associated with different brain disorders and cognitive dysfunction." (PMID 36830773, 2023). "Therefore, a better understanding of the role of COMT in cognitive processes could improve the development of potential therapeutic strategies for patients with AD and other brain disorders." (PMID 36830773, 2023).
peripheral neuropathy (1 paper, 2012). A disorder affecting the peripheral nervous system. "A total of 90 markers in GSTP1, COMT, and TPMT and their adjacent genomic regions (±20 kb) were analyzed for associations with refractory TGCT after first course of chemotherapy, progression-free survival (PFS), overall survival (OS), peripheral neuropathy, and ototoxicity." (PMID 23248619, 2012). "This study examined the association between three genes involved in cisplatin metabolism, GSTP1, COMT, and TPMT, with TGCT outcomes and cisplatin-induced ototoxicity and peripheral neuropathy." (PMID 23248619, 2012).
COMT also shares sentences with these, for which no sentence is quoted: Parkinson's (13 papers); kidney disease (5); bipolar I disorder (4); alcohol addiction (2); anorexia nervosa (2); glioblastoma (2); Huntington disease (2); Hypercholesterolemia (2); hyperprolinemia (2); Hyponatremia (2); impulse control disorder (2); invasive breast carcinoma (2); opioid use disorder (2); osteoporosis (2); paraganglioma (2); pheochromocytoma (2); Tinnitus (2); tuberculosis (2); vitamin D deficiency (2); acute kidney injury (1); acute myocardial infarction (1); agranulocytosis (1); allergic asthma (1); Arthritis (1); Autoimmunity (1); benign breast disease (1); bipolar II disorder (1); bone sarcoma (1); brain cancer (1); bulimia nervosa (1).
A further 56 diseases each share a sentence with COMT in 1 paper.